MYD88 (MYD88 innate immune signal transduction adaptor)
Diseases named in the same sentence as MYD88 in open-access papers (continued):
Sharing a sentence is not in itself a finding about the gene and the disease.
tumor (continued). "We also detected the Myd88 expression level in the tumor samples above by IHC, and the Myd88 expression was increased in Lv-Lnc-Myd88-SMMC-7721 cells compared with the controls." (PMID 29022910, 2017). "Taken together, these findings offer evidence that MyD88 signaling effectively promotes angiogenesis and tumor growth in vivo." (PMID 28662055, 2017). "In the context of chemo- or radiotherapy, the expression of TLR4 and activation of MyD88 mainly on dendritic cells were crucial for efficient induction of anti-tumour immunity." (PMID 28300057, 2017). "Ablation of MyD88 expression leads to a distinctive secretion of many soluble mediators involved in the regulation of tumor vasculature." (PMID 28662055, 2017). "It would be of interest to compare the profiles of lymphocyte phenotypes, clonality and determine the presence of recurrent mutations (involving MYD88, CD79B and PIM1 genes) in the tumor, plasma and bone marrow." (PMID 28636991, 2017). "Overall, these finding indicates that MyD88 expression supports a secretory phenotype that contributes to sustain a proangiogenic tumor microenvironment." (PMID 28662055, 2017). "MyD88 signaling endows these cells with the paradoxical ability to exert both tumor-suppressing and tumor-promoting effects, capable of either eliciting a productive antitumor adaptive immunity or promoting a tumor-enhancing immunosuppressive response." (PMID 28662055, 2017). "Some recent works have uncovered cell-autonomous functions of MyD88 relevant to oncogenesis and tumor progression." (PMID 28662055, 2017). "Our results imply that cell-autonomous signaling through MyD88 is required to sustain tumor growth and underscore its function as an important positive modulator for tumor angiogenesis." (PMID 28662055, 2017). "Mutations in the MYD88, MET, and APC genes were found in tumor samples from 2 out of 11 patients who relapsed later, and none were found in patients without relapse (0/33) (p=0.054)." (PMID 28152507, 2017). "In conclusion, our study identified a novel Lnc-Myd88 which has positive relationship with neighbor tumor promoter Myd88 in human HCC." (PMID 29022910, 2017). "Our results imply that cell-autonomous signaling through MyD88 is required to sustain tumor growth and underscore its function as an important positive modulator of tumor angiogenesis." (PMID 28662055, 2017). "In conclusion, the TLR4-mediated MyD88-dependent signaling pathway is probably one of the APS-induced signal pathways underlying the immunoregulation and anti-tumor effects of APS both in vitro and in vivo." (PMID 28303957, 2017). "Many reports suggest that MyD88 induces protumor signal in tumor or transformed cells, but in dendritic cells MyD88 induces priming of T cells to regress tumor cells." (PMID 29041928, 2017). "Results showed that the mRNA and protein levels were obviously provoked by APS and LPS in the MyD88+/+ tumor-bearing mice, compared with those in the NS group (P < 0.05)." (PMID 28303957, 2017). "We surmised that microbial TLR agonist (such as LPS and beyond) enhanced ACT tumor treatment via MyD88-dependent signaling in irradiated animals only." (PMID 26885368, 2016). "Bacterial infection stimulates the TLR/MYD88 pathway in tumor tissues, which is essential to the development and maintenance of an inflammatory microenvironment in gastrointestinal tumors." (PMID 27409669, 2016). "Tumor destruction was significantly impaired in irradiated MyD88-/- mice (P < 0.02; black diamond vs. black circle) compared to irradiated WT mice." (PMID 26885368, 2016). "It has been shown that EOC cells bear TLR4 and MyD88, an adapter coupling TLR4 and that TLR4/MyD88 signaling induces the synthesis of immunosuppressive cytokines and facilitates tumor progression and immune evasion." (PMID 27118139, 2016). "Coexistence of MYD88 and ERK2 mutations would have undermined the theory that one of the main outcome of MYD88 activation in tumor formation is increase ERK1/2 activity." (PMID 27303665, 2016).
tumor (continued). "Not only a TLR3-specific (TICAM-1-dependent) signal but also TLR2 (MyD88) signal in DC triggered the expansion of CD11c+ CD8+ T cells in tumor-bearing mice." (PMID 27619885, 2016). "We show here that Mycoplasma hyorhinis contamination in tumor cell lines can substantially activate co-cultured bystander immune cells through a factor activating the MyD88 pathway." (PMID 26565413, 2015). "Significant tumor growth retardation by combination of fractionated RT, DTIC and HT was also observed in MyD88 KO mice and when injecting Apyrase simultaneously in tumor-bearing wild-type mice." (PMID 25973681, 2015). "This was in part dependent on HMGB1, because no upregulation of the activation markers was observed when using DCs of MyD88 KO mice (Figures 4a1 and b1) or when incubating the tumor cell SNs with anti-HMGB1 antibody, respectively." (PMID 25973681, 2015). "Paclitaxel, a known TLR4 ligand, leads to activation of TLR4/MyD88-dependent pathway that mediates chemoresistance and tumor progression in epithelial ovarian carcinoma (EOC)." (PMID 24452475, 2014). "Expression of TLR4 and MyD88 were assessed in situ on paraffin sections of normal ovarian tissue adjacent to tumor (n=12) and borderline (n=8) and malignant (n=24) tumors." (PMID 24527095, 2014). "As evidence for this, paclitaxel treatment and partial surgical de-bulking have been shown to augment the tumor growth of CD44+/MyD88+ ovarian CSCs in xenograft mice models via the pro-inflammatory TLR2-MyD88-NFκB pathway." (PMID 25495823, 2014). "Most studies have indicated that activation of the TLR/MyD88 pathway is related to poor prognosis; however, this pathway can also suppress cell proliferation and tumor growth." (PMID 25360699, 2014). "During radiotherapy and chemotherapy, this soluble danger signal is released from dying tumor cells, activates TLR4 signaling through its MyD88 adaptor in DCs and promotes efficient processing and cross presentation of tumor antigens." (PMID 24434638, 2014). "The likely mechanism for paclitaxel-dependent tumor-activating effects is the ability of paclitaxel to activate TLR4/MyD88 signaling pathway." (PMID 24452475, 2014). "MyD88 expression was observed in both poorly- and well-differentiated tumour cells, and was strong near areas of necrosis." (PMID 24977712, 2014). "The expression of two microRNAs known to regulate the TLR4/MyD88 pathway was also evaluated in a subset of malignant tumour samples to explore their role as epigenetic modulators of this pathway." (PMID 24977712, 2014). "TLR activation can up-regulate the expression of co-stimulatory molecules and B7 family members through the Myeloid differentiation primary response gene 88 (MyD88)/TNF receptor associated factor (TRAF)-6, resulting in tumor evasion from the immune response." (PMID 24252328, 2013). "The experiments using B6 MyD88-/-/Trif-/- mice suggested that in addition to NK cells, other innate immune cells, such as DCs, are involved in the suppression of tumor formation of P29mtSAMP1 cybrids." (PMID 24098752, 2013). "The P29mtSAMP1 cybrids were able to form tumors in both B6 NKRed mice and B6 MyD88-/-/Trif-/- mice, although they showed longer latent periods than those of P29mtB6 cybrids to form measurable tumor volumes." (PMID 24098752, 2013). "We see that TLR4/MyD88 regulates the expression of IL-6, which shows its important role in many aspects of tumour growth." (PMID 22533866, 2012). "Our study for the first time revealed that TLR4, MyD88, and NF-κB were expressed in the tumor cells of a large number of OECs using immunohistochemistry." (PMID 22985132, 2012). "MyD88 has also recently been shown to be crucial for tumor promotion in models of spontaneous and carcinogen-induced (azoxymethane) intestinal tumorigenesis." (PMID 22985132, 2012). "It has been known that TLR4/MyD88 signalling in tumour cells itself has important roles as oncogenic factors." (PMID 22533866, 2012).
tumor (continued). "Recent reports revealed that TLR4/MyD88 signalling drives tumour growth and chemoresistance to paclitaxel in EOC." (PMID 22533866, 2012). "We found that TLR4, MyD88 and N-FκB were frequently expressed in tumor cells of OECs and that expression of TLR4, MyD88, TLR4/MyD88 and TLR4/MyD88/NF-κB was associated with overall survival in patients with OECs." (PMID 22985132, 2012). "MyD88 was expressed in the cytoplasm of the tumor cells and the positive expression of MyD88 was observed in 45 cases (36.6%) of OECs, and it had a significant correlation with tumor stage, tumor recurrence and histologic type." (PMID 22985132, 2012). "Silencing TLR4/MyD88 signalling in tumour cells results in reduced tumour formation, and the inhibition of tumour-cell apoptosis by MyD88-dependent TLR4 signalling was observed in EOC." (PMID 22533866, 2012). "Effect of oral administration of fucoidan on tumor growth and serum cytokine level in Myd-88 knockout mice." (PMID 23170088, 2012). "It was recently reported that TLR4/MyD88 signalling drives tumour growth in EOC with MyD88 positive expression." (PMID 22533866, 2012). "In this study, we included a large number of cases of OECs and various histologic subtypes of OECs and tried to demonstrate the expression of TLR4/MyD88 signaling pathway proteins in tumor cells using an immunohistochemical method." (PMID 22985132, 2012). "Recent clinical studies have indicated that low-grade serous EOC is relatively chemoresistant in the primary, neoadjuvant and recurrent settings, which was in agreement with our finding that high expression of MyD88 closely depended upon this tumor type." (PMID 22533866, 2012). "Positive MyD88 expression significantly correlated with shorter disease-free and overall survival for EOC (P < 0.0001 and P = 0.0031), and high MyD88 expression was significantly correlated with tumor metastasis (P = 0.0012) for EOC." (PMID 22533866, 2012). "We also detected the expression of TLR4 and MyD88 in the normal mucosa adjacent to the tumor, but the expression was quite weak." (PMID 22583829, 2012). "Similarly, the membrane-associated Hsp72 on tumor-derived exosomes was reported to mediate STAT3-dependent immunosuppressive function of MDSCs by triggering STAT3 activation in a Toll-like receptor- (TLR-) 2/MyD88-dependent manner, although the role of TLR2 in this process remains controversial." (PMID 22190973, 2011). "In multiple intestinal neoplasia (Min) mice, loss of MyD88 signaling reduced tumor numbers and sizes suggesting that MyD88 signaling contributes to tumor growth and progression." (PMID 20885960, 2010). "Silencing TLR4/MyD88 signalling in tumour cells not only results in reduced tumour formation but also leads to prolonged survival after subcutaneous tumour injection in mice." (PMID 20145615, 2010). "This study, for the first time, showed the clinicopathological significance of tumour cell self-TLR4/MyD88 expression in CRC." (PMID 20145615, 2010). "Recently, MyD88 has also been shown to be crucial for tumour promotion in models of spontaneous (Apcmin/+) and carcinogen-induced (azoxymethane) intestinal tumourigenesis." (PMID 20145615, 2010). "We see that TLR4/MyD88 regulates the expression of Cox-2, which shows its important role in many aspects of tumour growth." (PMID 20145615, 2010). "Certain innate sensors, such as nod1, appear to prevent tumour development; others, such as tlr4 and myd88, promote carcinogenesis." (PMID 19672421, 2009). "Hsa-miR-138-5p was enriched in immune signaling, Hippo, and apoptosis pathways, suggesting it may act as a tumor suppressor by targeting genes such as MYD88 and STAT1." (PMID 40869426, 2025). "The TLR4/Myd88/NF-κB signalling axis promotes the development of tumours." (PMID 39735680, 2025). "In detail, the microbes may stimulate MyD88-dependent myeloid cells to produce IL-1β and IL-23, activating Vγ6+ Vδ1+ γδT cells to produce factors such as IL-17, leading to inflammation and tumor cell proliferation." (PMID 40185720, 2025).
tumor (continued). "Furthermore, tumor-derived exosomal heat shock protein 72 enhances MDSC expansion by activating STAT3 via TLR2/MyD88-dependent autocrine IL-6 production, reinforcing an immunosuppressive tumor microenvironment TME." (PMID 40861469, 2025). "The TLR4/Myd88/NF-κB axis promotes the development of tumours." (PMID 39735680, 2025). "Research has confirmed that IL-36β can promote the activation of CD8+ T cells by activating mTORC1 through PI3K/Akt, IKK, and MyD88 pathways, thereby enhancing the anti-tumor immune response and laying the groundwork for the application of IL-36β in tumor immunotherapy." (PMID 40606972, 2025). "Recent studies revealed complex TLR4/MyD88 signaling interactions with tumor progression." (PMID 40703545, 2025). "Research on an H22 HCC mouse model highlighted the robust anti-tumor potential of salvianolic acid B. The findings revealed that salvianolic acid B not only curbed tumor growth but also mitigated inflammation-related immune activity by regulating the TLR4/MyD88/NF-κB pathway." (PMID 39972480, 2025). "Therefore, this review describes the involvement of MyD88 in tumor immune escape and disease therapy." (PMID 38785969, 2024). "Furthermore, MyD88 modulates the release of inflammatory and chemotactic factors, thereby shaping the tumor’s immune microenvironment." (PMID 38347830, 2024). "Importantly, r3LCMV improved tumor control in immunodeficient Rag1–/– mice and MyD88–/– mice, suggesting that multiple pathways contributed to the antitumoral effects." (PMID 38861331, 2024). "Multiple studies have underscored the substantial involvement of MyD88 in tumor metastasis." (PMID 38347830, 2024). "A stringent cut-off value is critical for clinical decisions, especially in cases for which the prior knowledge of the MYD88 L265P status in the tumor is unknown." (PMID 38566053, 2024). "Considering the critical driving force of MyD88 in cancer, targeting MyD88 may be a powerful strategy in the field of anti-tumor therapy." (PMID 38785969, 2024). "SESN1 functions as a new tumor suppressor gene in NB via a MyD88‐dependent TLR signaling pathway." (PMID 38516781, 2024). "Similarly, host MyD88 was absolutely required for LTX-315 to induce the establishment of long-term immunological memory downstream of tumor eradication." (PMID 38545099, 2024). "MyD88 is widely involved in tumor formation and is a key promoter of inflammatory development." (PMID 38785969, 2024). "MyD88 knockout in myofibroblasts significantly inhibited tumor growth." (PMID 38291436, 2024). "For example, Astragalus polysaccharide (APS) may regulate host immunity and exert anti-tumor effects by activating the TLR4-mediated MyD88-dependent signaling pathway." (PMID 38347830, 2024). "Our study indicates SESN1 functions as a new tumor suppressor gene via a MyD88‐dependent TLR signaling pathway in NB, and SENS1 and TLR signaling pathway may be new therapy targets for NB clinical treatment." (PMID 38516781, 2024). "Therefore, our understanding of MyD88-related tumor immune escape, promotion of M2 macrophage expression, and tumor cell DNA damage repair is slowly increasing." (PMID 38785969, 2024). "Mmp13 gene downregulation in the Myd88KO tumor group could be attributed to the fact that the MMP13 protumor activity may be mediated through the MyD88/ERK/NF-κB signaling pathway." (PMID 39000291, 2024). "MyD88 induces an anti-tumor immune response, thus inhibiting tumor development." (PMID 38785969, 2024). "Consequently, the MyD88/NF-κB pathway is involved in mediating drug resistance mechanisms in tumor cells." (PMID 38347830, 2024). "A rescue experiment showed that TLR4 overexpression could counteract the tumor-inhibitory roles of miR-5195-3p in CRC cell behaviors by enhancing TLR4/MyD88 signaling." (PMID 39390599, 2024). "Additionally, abnormal MyD88 signaling induces tumor cell proliferation and metastasis, which are closely associated with poor prognosis." (PMID 38785969, 2024).
tumor (continued). "In this review, we gathered critical evidence of MyD88 in regulating tumors and immune microenvironment, summarize recent research progress on MyD88 inhibitors, and reveal that residue ARG288 is highly likely to be an anti-tumor binding site between Myd88 protein and inhibitors." (PMID 38785969, 2024). "It is imperative that further research endeavors are undertaken to elucidate the intricate mechanisms through which MyD88 exerts its influence on the tumor immune microenvironment and to explore its potential applications in the development of novel treatments." (PMID 38347830, 2024). "Like Gc deficient hosts or WT mice gavaged with Gc-/- fecal matter, mice fed with a VitD3 high diet did not exhibit increased tumor resistance if rendered deficient in T and B cells, cDC1 or MyD88." (PMID 38662827, 2024). "Moreover, nodal metastasis tended to be associated with low levels of CD69, MYD88, and TLR4 mRNA expression within the tumor (p = 0.11, p = 0.06, and p = 0.06, respectively)." (PMID 36281585, 2023). "RT-qPCR was utilized to assess TLR4 and MyD88 expressions in pancreatic cells or tumor tissues." (PMID 37904102, 2023). "In addition, compared to the control group mice, the expression of miR-525-5p in the tumor tissue of the experimental group mice increased, and the protein expressions of Myd88 and NF-κB were decreased." (PMID 37953776, 2023). "Furthermore, the myeloid differentiation primary response 88 (MyD88) suppresses M2 gene expression in TAMs, resulting in an anti-tumor M1 phenotype." (PMID 38035101, 2023). "TLR4 function is similar to TLR2 because of the common signaling checkpoint (MyD88) they share, and activating NF-κB pathway, which could lead to tumor cell proliferation, apoptosis inhibition, and metastasis." (PMID 37283745, 2023). "In addition, curcumin also induces tumor cell apoptosis by suppressing the heat shock protein 60 (HSP60)/Toll-like receptor 4 (TLR-4)/myeloid differentiation primary response 88 (MYD88)/NF-κB pathway." (PMID 37373484, 2023). "Besides, both L. casei & L. reuteri and TAK-242 profoundly inhibited TLR4, MyD88, and Ki67 expressions in tumor tissues." (PMID 37904102, 2023). "In this situation, bacteria may activate myeloid differentiation factor 88 (MyD88) by engaging toll-like receptors on tumor-infiltrating myeloid cells and increasing the production of interleukin (IL)-23." (PMID 37190326, 2023). "Accordingly, we conclude that the observed antitumorigenic effect of targeting TLRs or epithelial specific MyD88/IKKβ is mainly due to the inhibition of the NF-κB pathway, and subsequent changes in the gradient of essential protumor versus anti-tumor cytokines as we and others have previously shown." (PMID 37283745, 2023). "It is also proposed that Tα1’s anti-tumor efficacy can be restored by blocking the MyD88 signaling pathway, raising the possibility that future research may examine ways to mitigate Tα1’s adverse effects when used to treat LC." (PMID 37701432, 2023). "However, based on the comparison of the tumor infiltration by FCM and the percentage of cells carrying MYD88 mutation by single-cell analysis, we were able to confirm that this alteration can be present in phenotypically normal B cells of WM patients." (PMID 37493341, 2023). "The MyD88, for instance, is an essential adaptor protein for Toll-like receptor (TLR) signaling, which can suppress M2 gene expression in tumor-associated macrophage (TAMs) and promote tumoricidal M1 phenotype through the activation of TLR4/MyD88/NF-κB pathway." (PMID 37476181, 2023). "Additionally, our findings support that the epithelial cell specific knockout of downstream signaling pathways to TLRs, MyD88, and IKKβ, also suppresses the tumor promoting effect of COPD-like lung inflammatory microenvironment." (PMID 37283745, 2023).